MTOR (mechanistic target of rapamycin kinase)
Diseases named in the same sentence as MTOR in open-access papers (continued):
Sharing a sentence is not in itself a finding about the gene and the disease.
lung cancer (continued). "The enhanced expression of slc10a2 triggered the expression of PPARγ, which ultimately caused an increase in PTEN expression and decrease in mTOR expression, implying that bexarotene decreases lung cancer cell survival through the slc10a2/PPARγ/PTEN/mTOR signaling pathway." (PMID 35631448, 2022). "Furthermore, tumor suppressor liver kinase B1 (LKB1) as a negative regulator of mTOR signaling was specifically identified as being commonly mutated in lung cancer, highlighting a potential role of the mTOR pathway in the development of lung carcinogenesis." (PMID 36428613, 2022). "Additionally, bleomycin down-regulates PTEN and activates PI3K/AKT/mTOR to cause senescence in lung cancer cells." (PMID 36139919, 2022). "Exosomes derived from lung cancer cells confer cisplatin resistance to other cancer cells and are associated with decreased expression of miR-100-5p which negatively regulates mammalian target of rapamycin (mTOR) expression." (PMID 34281588, 2021). "Moreover, we demonstrated that oversulfation of fucoidan enhanced its activity against lung cancer cells and determined that the underlying mechanism likely involves the Akt/mTOR/S6 pathway." (PMID 33921340, 2021). "Of note, mTOR upregulation is also considered a cause of resistance to EGFR-inhibitors in lung cancer patients, implying that they might also display metabolic vulnerability." (PMID 32943635, 2020). "Targeting mTOR signaling may have added value in the treatment of lung cancer, as mutations that promote mTOR signaling, such as alterations in the PI3K-AKT pathway, are among the most frequent activations in lung cancer." (PMID 30634602, 2019). "mTOR inhibitors are reported to have a significant risk for pneumonitis (relative risk of 31 for mild- and 8.8 for grade 3-4), which questions their use in lung cancer, particularly in combination with RT." (PMID 28915708, 2017). "Furthermore, this association between mTOR and glucose uptake has also been observed in lung cancer cells, specifically with uptake of [18F]FDG." (PMID 25561013, 2015). "Since the activation of the PI3K/AMPK/AKT/mTOR pathway is shown to cause the development of a more aggressive lung cancer phenotype which correlates to poor prognosis for patients, we assessed whether 21α-MMD affects these signals." (PMID 26098947, 2015). "Growing evidence supports abnormally activated mTOR to play an important pathogenic role in lung cancer associated with both KRAS and EGFR mutations and may provide a mechanism of resistance to treatment with EGFR inhibitors." (PMID 24593867, 2014). "Another downstream regulator of the PI3K pathway, the mammalian target of rapamycin (mTOR), was found to be mutated in more than 30% of 188 lung adenocarcinomas and is also frequently activated in lung cancer cell lines, and especially in these harboring genetic mutations." (PMID 24281308, 2012). "In addition, lung cancer cell lines harboring PIK3CA or PTEN mutations were sensitive to dual PIK3CA/mTOR inhibitors, which raises the hope that patients with mutations in the PI3K pathway may benefit from this type of targeted therapy in the future." (PMID 26068980, 2015). "CA has been reported to suppress the STAT3 signaling pathway through ROS generation and inhibit the phosphoinositide 3‐kinase/Akt/mTOR signaling pathway in colon cancer and lung cancer." (PMID 41513589, 2026). "The results indicate that treatment with SM-3 reduced the activation of mTOR and Akt in lung cancer cells, as evidenced by lower levels of both phosphorylated and total protein expressions compared to the parent compound, Res." (PMID 40287470, 2025). "Our work supports a previous study in which TAK‐228 and other mTOR inhibitors were found to increase PD‐L1 in lung cancer cell lines as well as other cancer cell types." (PMID 39258533, 2025).
lung cancer (continued). "In this study, we identified a significant association between cisplatin resistance and elevated LINC00511 expression, coupled with activation of the PI3K/AKT/mTOR pathway in lung cancer cells." (PMID 41480385, 2025). "According to our confirmation experiments, our interesting drug SM-3 effectively targets CSCs population in lung cancer via inhibiting mTOR/Akt pathway." (PMID 40287470, 2025). "Additional organoids experiments will be conducted to verify CSCs inhibition in lung cancer organoids via the mTOR/pAkt pathway." (PMID 40287470, 2025). "Another piRNA, piR‐55490, was recognised for its role in inhibiting lung cancer cell growth by attaching to the 3′ UTR region of mammalian target of rapamycin (mTOR) mRNA." (PMID 40714929, 2025). "In non-small cell lung carcinoma, piR-651 increased the expression of Cyclin D1 and CDK4 to promote tumor progression, while piR-55490 inhibited cell proliferation in lung cancer cells by targeting the 3′ UTR (untranslated region) of mTOR mRNA." (PMID 41154843, 2025). "Collectively, our results identify β-elemene as a promising therapeutic agent for overcoming cisplatin resistance in lung cancer by targeting the LINC00511/PI3K/AKT/mTOR axis." (PMID 41480385, 2025). "The results showed that SM-3-treated lung cancer cells exhibited reduced expression of mTOR and its phosphorylated form (Ser2448) compared to those treated with Res." (PMID 40287470, 2025). "We investigated the effectiveness of mammalian target of rapamycin (mTOR) inhibitors in canine lung cancer upon PI3K/AKT/mTOR activation in three canine PC cell lines and three mTOR inhibitors (AZD8055, temsirolimus, and everolimus) in vitro and in vivo." (PMID 40563640, 2025). "STAT3, a key transcription factor in lung cancer, drives tumour growth and immune suppression via the mTOR and JAK pathways." (PMID 40407951, 2025). "This mTOR inhibition promotes autophagic cell death in lung cancer cells while suppressing CSCs traits." (PMID 40287470, 2025). "In summary, the introduction of methyl and methoxy functional groups on Res to create SM-3 effectively suppressed cancer spheroids and organoids formation in lung cancer cells by targeting the upstream mTOR/pAkt pathway." (PMID 40287470, 2025). "The identification and validation of a reliable biomarker mirroring clinically meaningful PI3K/mTOR/AKT inhibition represents a compulsory aim in lung cancer." (PMID 41221490, 2025). "The small-molecule inhibitor JPH203 blocks the AKT/mTOR pathway, leading to the suppression of lung cancer stem cell growth and a reduction in tumor sphere size." (PMID 40417000, 2025). "The protein levels of Akt and mTOR were analyzed in lung cancer cells treated with SM-3 and Res using immunofluorescence." (PMID 40287470, 2025). "Mechanistically, our data show that β-elemene significantly downregulates LINC00511 expression, leading to inhibition of the PI3K/AKT/mTOR signaling pathway—a well-established driver of chemoresistance in lung cancer." (PMID 41480385, 2025). "For example, RVT has been shown to reverse tumor chemoresistance in lung cancer by inhibiting the PI3K/AKT/mTOR pathway, thereby enhancing cisplatin sensitivity—mechanistically consistent with our observations regarding β-elemene." (PMID 41480385, 2025). "Collectively, this study underscores the therapeutic potential of THQ derivatives, particularly compound 10e, as promising mTOR inhibitors with potential applications in lung cancer treatment." (PMID 40075606, 2025). "Meanwhile, LARP1 is recognized for its role in facilitating the metastasis of non‐small cell lung cancer via the activation of the mTOR pathway." (PMID 39786317, 2025). "Mechanistically, c-kit was found to regulate the AKT/mTOR/4EBP1/eIF4E axis, promoting stemness and gefitinib resistance in lung cancer cells." (PMID 39744423, 2025). "The recruited macrophages were found to support the growth of KRASG12D lung cancer cells in a mTOR-dependent way." (PMID 40611261, 2025).
lung cancer (continued). "Targeting mTOR is a key focus in developing new cancer therapies because its dysregulation is common in lung cancer, leading to tumor growth, resistance to cell death, and spread of cancer." (PMID 40075606, 2025). "It has been reported to target mTOR inhibition in various cancers, including oral, breast, and lung cancer." (PMID 40287470, 2025). "Baicalin also demonstrates dual effectiveness: in H1299 lung cancer cells, it induces Akt-dependent apoptosis by suppressing the Akt/mTOR pathway, while in HT-29 colon cancer cells, it triggers apoptosis by inhibiting c-Myc and oncomiRNAs." (PMID 40149916, 2025). "The molecular investigations indicated that c-kit regulated the AKT/mTOR/4EBP1/eIF4E axis, thus driving the transformation of the stemness phenotype in gefitinib-resistant lung cancer cells." (PMID 39744423, 2025). "Activation of mTOR also contributed to proliferative lung diseases such as lung cancer and pulmonary hypertension." (PMID 41142782, 2025). "This study highlights the therapeutic potential of Melittin with Erlotinib in targeting the JAK2/STAT3/mTOR/PI3K pathways for A549 lung cancer treatment." (PMID 40243485, 2025). "explored the mechanisms of miR-193a-5p in regulating lung cancer metastasis by downregulating the ERBB4/PIK3R3/mTOR/S6K2 signaling pathway." (PMID 40230863, 2025). "Previous studies have shown that targeting the AKT/mTOR signaling pathway can induce cell autophagy and death in gastric and lung cancers, offering potential therapeutic strategies." (PMID 40563327, 2025). "In brief summary, the PI3K/AKT/mTOR pathway plays a crucial role in regulating metabolic processes that support the growth and survival of lung cancer cells." (PMID 39953539, 2025). "In lung cancer, deregulation of mTOR signaling plays a key role in accelerating tumor progression and increasing malignancy." (PMID 40855114, 2025). "Molecular docking and dynamics simulations corroborated the in vitro results, establishing the compounds’ potential as therapeutic agents for targeting mTOR in lung cancer." (PMID 40075606, 2025). "This study has become the basis for the interest in combination therapies using cycloastragenol and inhibiting the AMPK/ULK1/mTOR pathway in lung cancer cells." (PMID 40362333, 2025). "Collagen prolyl 4-hydroxylase(P4H) is a dioxygenase that catalyzes 4-hydroxylation of proline, although it has been reported that P4HA2 inhibits the growth of lung cancer by enhancing mTOR stability." (PMID 39920992, 2025). "The PI3K/AKT/mTOR pathway is central to this metabolic reprogramming in lung cancer, orchestrating anabolic and catabolic processes to sustain rapid cell growth and survival." (PMID 39953539, 2025). "In non–small cell lung cancer (NSCLC) with EGFR mutations, mTOR expression levels were low to intermediate in most cases (62.5%), while a significant portion (37.5%) exhibited high mTOR expression." (PMID 40754657, 2025). "mEAK-7 is significantly elevated in the tumors and metastatic lymph nodes of NSCLC patients, and microRNA-1911-3p can target mEAK-7 to inhibit mTOR signaling in human lung cancer cells." (PMID 41262242, 2025). "To verify the inhibition of CSCs in lung cancer spheroids through the mTOR/pAkt pathway, we will conduct additional experiments using organoids." (PMID 40287470, 2025). "This article evaluated the synthesis, properties, and anticancer activity of CuNPs using fennel extraction and focused on their effects on human lung cancer via the PI3K/AKT/mTOR pathway." (PMID 39787250, 2025). "Treatment of lung cancer cells with SM-3 (50 μM) can induce autophagic cell death by reducing several proteins, including Akt and mTOR." (PMID 40287470, 2025). "This research underscores the potential of morpholine-substituted tetrahydroquinoline derivatives as promising mTOR inhibitors for targeted cancer therapy, particularly against lung cancer." (PMID 40075606, 2025).
lung cancer (continued). "In a mouse model, treatment with mTOR inhibitor rapamycin was connected to a 90% decrease in lung cancers brought on by carcinogens." (PMID 40248706, 2025). "In lung carcinoma, loss of CMTM4 significantly reduces tumor growth and impairs NF-κB, mTOR, and PI3K/Akt pathway activation." (PMID 39948411, 2025). "This process is likely due to the modulation of AMPK/mTOR signaling pathway by C3G to regulate cellular fatty acid metabolism and reduce intracellular lipid accumulation which affects the growth of lung cancer cells." (PMID 38716355, 2024). "This mutation also contributes to resistance to EGFR-TKIs in lung cancer by activating downstream effectors such as AKT and mTOR." (PMID 39743996, 2024). "It has been demonstrated that inhibition of mTOR increased the radiosensitivity of some malignancies, such as lung cancer cells." (PMID 38965615, 2024). "For example, genetic changes affecting PTEN can drive lung tumorigenesis by activating mTOR/Akt pathways, leading to lung cancer metastasis." (PMID 38877005, 2024). "While no other studies have examined the effects of CA treatment on prostate cancer cell mTOR and p70 S6K, CA inhibited mTOR in hepatoma, lung cancer and gastric cancer cells." (PMID 38732504, 2024). "In the A549 human lung cancer cell line, eriodictyol induced mitochondrial apoptosis and G2/M cell cycle arrest and inhibited mammalian target of rapamycin (mTOR)/PI3K/AKT cascade." (PMID 39683630, 2024). "AREG, in turn, upregulates the glutamine transporter SLC1A5 and promotes the accumulation of glutamine-derived TCA cycle metabolites via the EGFR/PI3K/AKT/mTOR signaling pathway, thereby promoting lung cancer cell growth and proliferation." (PMID 38904011, 2024). "Hyperactivation of the mTOR complexes resulting from the genetic alterations of the members of the PI3K/Akt/mTOR signaling cascade is frequently seen in solid tumors, including the most common histological subtypes of lung cancer." (PMID 38339294, 2024). "Further, emerging evidence has suggested that mTOR signaling contributes to drug resistance in melanoma, breast cancer, lung cancer, and head and neck cancer." (PMID 38560690, 2024). "Isoliquiritigenin, a compound found in licorice, induces growth inhibition and cell apoptosis in A549 lung cancer cells by inhibiting the activation of the PI3K/AKT/mTOR signaling pathway." (PMID 38245694, 2024). "IL-7 was discovered to lower Beclin-1 levels and activate the PI3 K/Akt/mTOR pathway in lung cancer cells." (PMID 39650649, 2024). "Our previous study showed that SHOC2 also negatively regulated the mTORC1 signal by competing with mTOR for Raptor binding in lung cancer cells." (PMID 39871893, 2024). "GPER1, in reverse, is found to enhance the phosphorylation of AKT/mTOR pathway leading to its activation in breast, ovarian and lung cancer resulting in increased cell proliferation in these types of cancers." (PMID 39252786, 2024). "This is a traditional (narrative) review based on Pubmed and Google Scholar searches for the following keywords: Rictor, RICTOR amplification, mTORC2, Rictor complexes, lung cancer, metastasis, progression, mTOR inhibitors." (PMID 38339294, 2024). "Cisplatin (CDDP), an anti-cancer drug most effective against tumor cells in the resting period, and β- elemene, which inhibits the PI3K/AKT/mTOR axis, were co-treated to lung cancer cell lines such as A549 and NCI-H1650." (PMID 39349424, 2024). "In lung cancer targeting, the KRAS G12C mutation has been shown to have add-on effects/synergy with other treatments such as mTOR and IGF1R inhibitors in vitro and in vivo." (PMID 38607041, 2024). "As a leucine sensor, LARS activates mTOR signalling for protein synthesis, and is up‐regulated in lung cancer." (PMID 38769668, 2024).
lung cancer (continued). "In vitro, C3G intervention was found to significantly inhibit the proliferation and apoptosis of lung cancer cells by regulating fatty acid metabolism through modulating the AMPK/mTOR signaling pathway." (PMID 38716355, 2024). "We demonstrated that this positive feedback loop between IGF2BP2 and SLC7A5 promotes lung cancer radioresistance through the AKT/mTOR pathway." (PMID 38281999, 2024). "BEZ235, a dual PI3K and mTOR inhibitor, has been found to be an effective suppressor of lung cancer." (PMID 39339205, 2024). "In lung cancer, tumors with acquired chemoresistance showed constitutive activation of mTOR signaling and autophagy defects, with high steady-state levels of LC3 and p62." (PMID 38560690, 2024). "MET decreased by dictamnine suppresses lung cancer cell growth by downregulating PI3K/AKT/mTOR and MAPK signaling pathways." (PMID 39519229, 2024). "Recently, it has been revealed that the PI3K/AKT/mTOR signaling pathway influences the aggressiveness of lung cancer." (PMID 39349424, 2024). "ANXA2 is also associated with several classical cancer-related pathways such as PI3K/Akt signaling, Akt/mTOR signaling, and NF-κB signaling pathways in lung cancer, gastric cancer, and GBM respectively." (PMID 38658569, 2024). "We demonstrated that IGF2BP2 promotes lung cancer radioresistance by forming a positive feedback loop with SLC7A5 to activate the AKT/mTOR pathway." (PMID 38281999, 2024). "Curcumin can induce autophagy through the inhibition of the PI3K/AKT/mTOR axis, as has been previously shown in studies involving human lung cancer and glioblastoma cells." (PMID 38672636, 2024). "Bioreducible polymer was used to encapsulate siRNA inhibiting mTOR and it exhibited strong potential to deliver siRNA to lung cancer cells." (PMID 39339205, 2024). "White peony extract induces cell apoptosis and autophagic cell death in human lung cancer cells by inhibiting the PI3K/Akt/mTOR pathway." (PMID 38245694, 2024). "They focused on miR-100-5p, which is most downregulated in EVs derived from resistant lung cancer cells, and identified the mammalian target of rapamycin (mTOR) as a target gene using several bioinformatics methods." (PMID 38318528, 2024). "A mechanistic investigation demonstrated that exposing lung cancer cells to CLs downregulated the phosphorylation of Akt and mTOR, as well as c-Myc expression." (PMID 38672078, 2024). "The PI3K/AKT/mTOR pathway is frequently altered in lung cancer and it is assumed that aberrant activation of this pathway contributes to tumour growth, tissue invasion, metastasis and drug resistance." (PMID 38575987, 2024). "For example, in osteosarcoma, TRIM22 can impact autophagy by modulating the ROS/AMPK/mTOR signaling pathway, while in lung cancer, it can influence epithelial‐mesenchymal transition through the AKT/GSK3β signaling pathway." (PMID 38468469, 2024). "Resistance to cisplatin has been reported to be associated with the induction of Akt expression in colon cancer, and Akt/mTOR pathway inhibition reduced cisplatin resistance in ovarian and lung cancer cells." (PMID 38399413, 2024). "Overexpression of METTL3 in lung cancer cells activates the PI3K/AKT/mTOR pathway and mTOR-mediated protein synthesis, promotes the proliferation and metastasis of cancer cells, and is a poor prognostic factor for lung cancer patients." (PMID 39289775, 2024). "The Akt/mTOR signaling pathway can activate c-Myc, which plays a critical role in promoting the self-renewal and survival of CSCs in various cancers, including lung cancer." (PMID 38672078, 2024). "It has been reported that hyperoside inhibits the AKT/mTOR/P70S6K pathway while activating the ERK1/2 pathway to induce autophagy in A549 lung cancer cells." (PMID 39573995, 2024).